ENSG00000252923
Synonyms: LOC124900529
Gene: Small Cajal body-specific RNA gene on chromosome 2 (196,686,148 to 196,686,330, reverse strand). Ensembl gene ENSG00000252923.
Gene Ontology:
Biological process: RNA processing
Cellular component: nucleolus